UCK2 (uridine-cytidine kinase 2)
Diseases named in the same sentence as UCK2 in open-access papers (continued):
Sharing a sentence is not in itself a finding about the gene and the disease.
cancer (28 papers, 2014 to 2025). A tumor composed of atypical neoplastic, often pleomorphic cells that invade other tissues. "We found a significant positive association between RNA stemness scores (RNAss) and UCK2 expression in most cancers, as shown in." (PMID 39931080, 2025). "We found that UCK2 expression was associated with glycolysis by GSEA analysis method in many cancers." (PMID 39931080, 2025). "In conclusion, we perform multi-omics pan-cancer analyses of UCK2 and explored the of UCK2 in gene mutation, TMB, MSI, clinical prognostic value, immune cell infiltration, and drug sensitivity." (PMID 39931080, 2025). "Meanwhile, GO, KEGG and GSEA analysis demonstrated that UCK2 expression was strictly linked with MMR in many cancers." (PMID 39931080, 2025). "The results of our study revealed significant differences in gene expression during the development of various cancers, leading us to consider the potential of UCK2 gene as diagnostic and prognostic markers in pan-cancer." (PMID 39931080, 2025). "On the contrary, the expression of UCK2 is strongly positive association with methyltransferase in various cancers." (PMID 39931080, 2025). "The expression of UCK2 is significantly associated with the pathologic stage in five types of cancer: NHSC, KIRP, LUAD, LUSC, TGCT." (PMID 39931080, 2025). "Specifically, our GSEA analysis revealed a significant association between UCK2 expression and IFNγ in four different types of cancer." (PMID 39931080, 2025). "Recent studies have shown that UCK2 was a cancer-promoting factor in HCC and was associated with adverse clinical outcomes of HCC." (PMID 35957801, 2022). "Uridine-cytidine kinase 2 is an enzyme that is overexpressed in abnormal cell growth and its implication is considered a hallmark of cancer." (PMID 28103302, 2017). "UCK2 have been reported to be expressed only in the placenta and its over expression have been implicated in several rapidly proliferating cancer cells." (PMID 27070566, 2016). "Uridine-cytidine kinase 2 is implicated in uncontrolled proliferation of abnormal cells and it is a hallmark of cancer, therefore, there is need for effective inhibitors of this key enzyme." (PMID 27070566, 2016). "While a positive association between UCK2 expression and DNMTs in 30 other cancers." (PMID 39931080, 2025). "UCK2 (Uridine-Cytidine Kinase 2) is a promising prognostic marker for malignant tumors, but its association with immune infiltration and cancer stemness in pan-cancer remains to be fully understood." (PMID 39931080, 2025). "Interestingly, we identified major histocompatibility complex (MHC)-II related to gene with an exceptionally high association with UCK2 in various cancers." (PMID 39931080, 2025). "In this study, we aim to investigate the association between UCK2 and DNA repair across pan-cancer." (PMID 39931080, 2025). "Loss of function of UCK2 may lead to an increase in errors in the repair process, which can exacerbate genomic instability in cancer cells." (PMID 39931080, 2025). "Our findings revealed that UCK2 is significantly co-expressed on cancer cells and stromal cells in multiple cancer types, with particularly high expression observed on T cells, macrophages, cancer-associated fibroblasts, endothelial cells, cancer cells and fibroblasts." (PMID 39931080, 2025). "However, the molecular mechanism involving UCK2 associated with cancer progression and chemoresistance in iCCA remains unclear." (PMID 39179560, 2024). "UCK1 is present in both cancer and normal cells, whereas UCK2 is preferentially expressed in various cancer cells, including neuroblastoma cells." (PMID 40804482, 2025). "UCK2 uses the DNA repair pathway to become a therapeutic target for cancer through several pathways, such as accurate and timely DNA repair during the occurrence of HRR and MMR, which is essential to maintain genomic stability." (PMID 39931080, 2025).
cancer (continued). "Elevated UCK2 expression was strongly correlated with adverse prognostic outcome across multiple cancer types." (PMID 39931080, 2025). "UCSC database is a very useful for explore data from TCGA and other cancer genomics datasets, The data we explored at the UCK2 transcriptome level came from TCGA data in the UCSC database." (PMID 39931080, 2025). "It was observed that UCK2 expression was comparatively higher in the C4 immune subtype (Lymphocyte Deplete) when compared to other subtypes in several cancers, such as LUAD, STAD, SARC, and LUSC." (PMID 39931080, 2025). "UCK2 expression was observed to be high in most cancers and was remarkably related to the prognosis of pan-cancers." (PMID 39931080, 2025). "This study has conducted a thorough analysis of UCK2 profiles, including its clinical features, single-cell sequencing, and particularly its roles in DNA repair and cancer immunity." (PMID 39931080, 2025). "Instead, compared with cancer tissues, the UCK2 gene is highly expressed in normal tissues, including GBM, KIRC, LIHC, THCA, and Lymphadenoma." (PMID 39931080, 2025). "Intriguingly, UCK2 was identified as a protective factor in specific cancer subtypes, including CHOL, DLBC, OV, STAD." (PMID 39931080, 2025). "In the pan-cancer analysis, UCK2 exhibited the highest level of enrichment in CESC and the lowest level of enrichment in KICH." (PMID 39931080, 2025). "Despite the reported involvement of UCK2 in certain cancer types, there remains a significant dearth of research regarding its impact across the entire spectrum of cancer." (PMID 39931080, 2025). "We use the experimental method of IHC to further test and verify the expression of UCK2 in various cancers." (PMID 39931080, 2025). "The correlations of UCK2 with prognosis, genetic instability, DNA repair, cancer stem cell characteristics, and immune cell infiltration were investigated." (PMID 39931080, 2025). "Further research is necessary to fully comprehend the functions and mechanisms of UCK2 gene in cancer development and progression." (PMID 39931080, 2025). "Moreover, we found that UCK2 expression was strongly correlated with the kinds of types of infiltrating immune cells and immune stromal (T cells, monocytes, mast cells, and macrophages, cancer-associated fibroblasts, endothelial cells, cancer cells and fibroblasts)." (PMID 39931080, 2025). "This study examined the relationship between UCK2 mRNA expression and long-term survival across various cancer types." (PMID 39931080, 2025). "To further explored the UCK2 expression in cancer immunity, we conducted a study investigating its correlation with the level of infiltration of 28 immune cell types by the ssGSEA method and Hmisc function." (PMID 39931080, 2025). "Targeting nucleotide metabolism is a classic anti-cancer strategy, thus establishing a solid theoretical foundation for UCK2 as a target of ICT." (PMID 41357200, 2025). "UCK2 overexpression promotes cancer cell proliferation and metastasis by activating the Wnt/β-catenin." (PMID 39179560, 2024). "Uridine-cytidine kinase 2 (UCK2) is proved to promote progression and drug resistance of various carcinomas by regulating pyrimidine metabolism." (PMID 39179560, 2024). "UCK1 is expressed universally in various tissues, while UCK2 is known to be expressed only in human placenta and several types of cancers." (PMID 37297025, 2023). "While HSPA1A and UCK2 have been discussed in the context of diseases such as cancer, their involvement in puberty remains to be reported." (PMID 35831802, 2022). "High levels of UCK2 promote cancer cell proliferation and metastasis by activating the Wnt/β-catenin and EGFR–AKT signalling pathways." (PMID 36447138, 2022). "UCK2 upregulated in cancer is partly due to demethylation, which contributes to resistance of cancer to 5-azacytidine treatment." (PMID 36447138, 2022).
cancer (continued). "Meanwhile, when UCK1 expresses universally in various tissues, UCK2 exclusively expresses in human placenta and several types of cancers." (PMID 35669416, 2022). "Although UCK2 is overexpressed in many cancer types, the The Cancer Genome Atlas (TCGA) pan-cancer analysis on UCK2 is missing." (PMID 35669416, 2022). "UCK2 is essential for maintaining the stability of mTOR, and downregulation of UCK2 can specifically inhibit mTOR signalling pathway-related metabolic reprogramming of cancer cells." (PMID 36447138, 2022). "Although UCK2 is only expressed in human placenta and testis, upregulation of UCK2 has been observed in many cancers." (PMID 35392276, 2022). "By harnessing the catalytic activity of UCK2, several cytotoxic ribonucleoside analogs, such as TAS-106 and RX-3117, have been developed for UCK2-mediated cancer chemotherapy." (PMID 35669416, 2022). "Cytotoxic agents that target UCK2 enzyme activity to induce cancer cell death are currently investigated in some clinical trials." (PMID 34523732, 2021). "As a rate-limiting enzyme of salvage pyrimidine biosynthesis, UCK2 overexpression has been reported in many types of cancers including HCCs40, but the biological function of UCK2 in HCCs is underexplored." (PMID 33277463, 2020). "UCK2 up-regulation has been detected in several types of cancers including pancreatic tumor, colorectal cancer, neuroblastoma, breast cancer, and HCCs28,37,40." (PMID 33277463, 2020). "Due to the selective expression of UCK2 in cancer cells, a selective inhibition of this key enzyme necessitates the discovery of its potential inhibitors for cancer chemotherapy." (PMID 28103302, 2017). "The key to this selective targeting is the selective inhibition of the UCK2 enzyme, which has proven to be the main targeted protein in this cancer therapeutic." (PMID 28103302, 2017). "Nucleoside analogues are being used to treat different cancer cells via their phosphorylation catalyzed UCK2." (PMID 27070566, 2016). "This study aims to shed light on the role and possible mechanism of UCK2 in pan-cancer." (PMID 39931080, 2025). "The gene UCK2 demonstrated significant expression levels in 27 type of cancer samples, it exhibits high expression levels across in 23 cancer types and low expression levels across in 4 cancer types." (PMID 39931080, 2025). "Additionally, positive relationships were observed between UCK2 expression and mismatch repair genes, homologous recombination repair genes, and cancer stemness across different cancer types." (PMID 39931080, 2025). "We noted that UCK2 had significant correlations with the sensitivity to various anti-cancer drug." (PMID 39931080, 2025). "Moreover, UCK2 expression showed a positive correlation with CNV in 31 out of 33 cancers, with the exception LUAD and LAML." (PMID 39931080, 2025). "Although our findings suggest that a correlation between aberrant UCK2 expression, immune cell infiltration, and prognosis of human cancers, it remains unclear whether UCK2 may directly influences patient survival through an immune response." (PMID 39931080, 2025). "As the same time, an article suggests that the gene UCK2 should be used for pan-cancer research." (PMID 39931080, 2025). "Inhibition of the UCK2 enzyme may interfere with DNA synthesis in cancer cells, thereby inhibiting the growth and proliferation of cancer cells." (PMID 39931080, 2025). "Moreover, in this study, we have conducted a comprehensive analysis of the correlations between TMB, MSI and HRD with UCK2 in pan-cancer." (PMID 39931080, 2025). "Furthermore, our findings provide a comprehensive understanding of the roles of UCK2 in cancers and offer valuable insights for the development of novel targeted therapies." (PMID 39931080, 2025). "Therefore, the role of UCK2 in immune interaction and coordination in other cancers deserves further exploration." (PMID 39931080, 2025).
cancer (continued). "Previous study confirmed that UCK2 is essential for maintaining the stability of mTOR and downregulation of UCK2 can specifically inhibit mTOR signaling pathway-related metabolic reprogramming of cancer cells." (PMID 39179560, 2024). "UCK2, an important rate-limiting enzyme in the rescue pathway of pyrimidine-nucleotide biosynthesis, exhibits a series of biological function of promoting cancer proliferation, invasion and metastasis." (PMID 39179560, 2024). "In addition, targeting UCK2 can relapse amino acid metabolism to decrease the resistance of cancer cells to T-cell-mediated killing." (PMID 36447138, 2022). "Therefore, the selective expression of UCK2 in cancer cells makes it a potential target for cancer chemotherapy." (PMID 27070566, 2016). "Thus, we calculated the ESTIMATE of UCK2 in various types of cancer." (PMID 39931080, 2025). "However, the role of UCK2 in pan-cancer among humans have yet to identified." (PMID 39931080, 2025). "our findings revealed strong positive correlations between UCK2 expression and T helper type 2 cells, activated CD4+ T cells, central memory CD8+ T cells, and memory B cells across multiple types of cancer." (PMID 39931080, 2025). "Our results indicated a positive correlation between UCK2 expression and activated memory CD4+ T cells, T follicular helper cells, M0 macrophages, M1 macrophages, and activated mast cells across several cancers." (PMID 39931080, 2025). "However, the mechanism of UCK2 upregulation in cancer remains unclear." (PMID 36447138, 2022). "ECyd is activated by UCK2 followed by the inhibition of RNA polymerase I, II and III, which finally leads to the suppression of cancer cell proliferation." (PMID 25087851, 2014). "UCK2 may participate in MMR or HDR, glycolysis, DNA methylation or methyltransferase, to promote cancer stem cell." (PMID 39931080, 2025). "However, we did not observe this correlation in CESC, CHOL and UCS, Interestingly, we also found positive correlations between UCK2 expression and HRR signature in most cancers, including UVM, as shown in." (PMID 39931080, 2025). "Among these 18 cancers, the expression of UCK2 exhibited a negative correlation with DNA methylation levels in 16 cancers, while in 2 cancers, it showed a positive correlation." (PMID 39931080, 2025). "In our study, we noticed that UCK2 expression is significantly negative correlation with DNA methylation in several cancers." (PMID 39931080, 2025). "We observed an overall significant negative correlation between UCK2 expression and the ImmuneScore, ESTIMATEScore, StromalStore in various cancers." (PMID 39931080, 2025). "In addition, downregulation of UCK2 increases the expression of major histocompatibility complex (MHC) I, which sensitizes cancer cells to T-cell-dependent killing." (PMID 36447138, 2022). "Thus, we speculated that UCK2 plays a role in mediating the upregulation of MHC II expression by IFN-γ, thereby preserving cancer stem cells." (PMID 39931080, 2025). "Furthermore, our analysis included the examination of correlations between UCK2 expression and key genes related to major histocompatibility complex (MHC), immune activation, immune suppression, chemokines, and chemokine receptors across various cancer types." (PMID 39931080, 2025).
cancer (continued). "In contrast, we observed negative correlations between UCK2 expression and resting memory CD4+ T cells, monocytes, M2 macrophages, resting mast cells in various cancers." (PMID 39931080, 2025). "UCK2 can non-metabolically activating EGFR-AKT signaling pathway to promote HCC progression and may provide novel UCK2-based therapeutic strategies for cancer treatment." (PMID 39179560, 2024). "However, in a panel of 60 cancer cell lines, AZA sensitivity correlated with UCK2 but not UCK1 expression." (PMID 36834962, 2023). "In addition to the metabolic feature of UCK2 which has been employed for cancer treatment, our recent study has demonstrated that UCK2 can non-metabolically activating EGFR-AKT signaling to promote HCC progression, which may provide novel UCK2-based therapeutic strategies for cancer treatment." (PMID 35669416, 2022).
infection (6 papers, 2007 to 2025). The state of being infected such as from the introduction of a foreign agent such as serum, vaccine, antigenic substance or organism. "Genes involved in pyrimidine metabolism (RRM2, CTPS1, TK1, NME1, NME2, and UCK2) were induced after infection with swH1N1 compared to huH1N1." (PMID 39247193, 2024). "Furthermore, other genes related to the pyrimidine pathway, namely NME1, NME2, and UCK2, were significantly higher expressed after infection with the swH1N1 relative to the pigs infected with huH1N1, albeit occasionally with modest fold changes." (PMID 39247193, 2024). "UCK2 was knocked out in Huh7 cells by infection with a lentiviral vector to express the gRNAs." (PMID 38896142, 2024).
UCK2 also shares sentences with these, for which no sentence is quoted: adult T-cell leukemia (1 paper); atopic dermatitis (1); cervical squamous cell carcinoma (1); cholangiocarcinoma (1); esophageal cancer (1); hematopoietic cancers (1); histiocytic lymphoma (1); intrahepatic cholangiocarcinoma (1); ischemic heart disease (1); Myocardial fibrosis (1); neuroblastoma (1); retinoblastoma (1); testicular germ cell tumor (1).